APOE (apolipoprotein E)
Diseases named in the same sentence as APOE in open-access papers (continued):
Sharing a sentence is not in itself a finding about the gene and the disease.
cardiovascular disease (continued). "This may explain the increased incidence of cardiovascular disease in patients with these mutant ApoE phenotypes." (PMID 23122424, 2012). "The present study explores whether the widely found cardiovascular diseases (CVD) risk effects of ACE I/D, APOE (ε2, ε3, ε4), eNOS-VNTR and LEP G2548A polymorphisms can be replicated in this specific population." (PMID 21244662, 2011). "This study, the largest to date, provides robust evidence of an association between plasma hsCRP and the APOE genotype, an association not explained by history of cardiovascular disease nor its risk factors." (PMID 20074603, 2010). "The absence of APOE expression is implicated in the modification of lipoprotein profiles, contributing to the manifestation of a spectrum of disorders ranging from cardiovascular diseases and neurological disorders to type II diabetes, compromised immune responses, and even a reduction in lifespan." (PMID 38540308, 2024). "Higher levels of circulating apoE are found in populations with increased risk of cardiovascular disease, although in many cases it is not clear whether this is contributed to by apoE in HDL, or in non-HDL fractions." (PMID 38879166, 2024). "However, the connection between APOE and cardiovascular disease (CVD) is less robust." (PMID 32346601, 2020). "Indeed, humans lacking functional ABCA1 have lower APOE levels and increased risk of AD and cardiovascular disease." (PMID 32005122, 2020). "Based on their reversible properties, the apoE disulfide-linked complexes may be committed to maintaining their redox status and regulating their functions, consequently impacting the pathophysiology of various apoE-related diseases such as AD and cardiovascular diseases." (PMID 30948502, 2019). "In this study population, lipid levels as well as the risk of cardiovascular disease are far lower than in affluent populations, which may explain why APOE does not affect survival here." (PMID 27356285, 2016). "As a major protein involved in lipoprotein metabolism and cardiovascular disease, ApoE might bidirectionally adjust action under the interaction of diet as environmental factors and genetic susceptibility, which has been detected in a variety of tissues, including liver, kidney, and brain." (PMID 25006576, 2014). "We could not find a statistically significant association between APOE and markers of cardiovascular disease." (PMID 23613766, 2013). "Cardiovascular disease highlights CDKN2B-AS1, LPA, and SH2B3; respiratory system disease features CHRNA3; psychiatric disorders highlight APOE, APOC1." (PMID 41166152, 2026). "ApoE was initially described as a lipid transport protein and major ligand for LDL receptors with a role in cholesterol metabolism and cardiovascular disease." (PMID 37529351, 2023). "Apolipoprotein E is a lipid transport protein and an important ligand for low-density lipoprotein (LDL) receptors with a function in cholesterol metabolism and cardiovascular diseases (CVD)." (PMID 37134097, 2023). "Finally, we had reported that the injection of ZBTB20 knockdown adenovirus in the tail vein of ApoE−/− mice fed with a Western diet could alleviate AS, indicating that the tail vein adenovirus injection is a potential method for treatment of cardiovascular diseases." (PMID 34136067, 2021). "ApoE functions as a ligand for low-density lipoprotein (LDL) receptors and plays a role in lipid metabolism; it has been well described in the context of cardiovascular diseases." (PMID 30890171, 2019). "We did not consider lipids as a confounding factor as earlier studies do not support the connection between APOE and BMI through lipids nor cardiovascular disease." (PMID 38496317, 2024). "Our characterization of a novel protective mechanism for APOE in human cardiovascular cells provides fresh insights into CVD mechanisms and may help inform development of intervention strategies for cardiovascular disorders." (PMID 37010884, 2023).
cardiovascular disease (continued). "In this analysis of 16,174 patients with cardiovascular disease, APOE genotype did not significantly moderate the relationship between evolocumab treatment and patient-reported or objectively assessed decline in cognition." (PMID 35404972, 2022). "ApoE was initially described to be a lipid transport protein, and major ligand for low-density lipoprotein (LDL) receptors with a role in cholesterol metabolism and cardiovascular disease." (PMID 35208189, 2022). "In addition, ApoE is described as a major ligand for LDL receptors with a role in cholesterol metabolism and cardiovascular disease." (PMID 36678541, 2022). "Overall, these studies suggest that a lack of ApoE is a susceptibility factor in ENM-induced lung inflammation and cardiovascular disease." (PMID 33022979, 2020). "The genes in the light cyan module identified in AD APOE ε4 non-carriers were enriched not only in neurological diseases but also in some other types of diseases, such as immunological and cardiovascular diseases with high rankings." (PMID 27462267, 2016). "Exercise was an effective non-pharmacologic approach to slow cardiovascular disease in the presence of kidney disease in the apolipoprotein E knockout mouse." (PMID 25799529, 2015). "Moreover, Milliplex MAP assays were performed to measure apoAI, apoE and apoCIII, proteins known to be constituents of HDL and to be related to cardiovascular disease." (PMID 22978374, 2012). "The association between APOE and CRP was not materially affected by adjustment for age, sex, history of cardiovascular disease, or cardiovascular risk factors." (PMID 20074603, 2010). "However, genes within the two modules of AD APOE ε4 carriers were not highly enriched in immunological and cardiovascular diseases." (PMID 27462267, 2016). "Unlike the modules identified in AD APOE ε4 carriers, genes of the light cyan module identified in AD APOE ε4 non-carriers were enriched in some other types of diseases, such as immunological and cardiovascular diseases, in addition to the primarily enriched neurological diseases." (PMID 27462267, 2016).
neurodegenerative disease (339 papers, 2006 to 2026). A disorder of the central nervous system characterized by gradual and progressive loss of neural tissue and neurologic function. "Human genetic variants, particularly the APOE ε4 allele, contribute to the onset and progression of neurodegenerative diseases by altering lipid metabolism and organelle function." (PMID 40301465, 2025). "A notable finding of our study is that the pro-inflammatory molecular phenotype associated with APOE ε4 extends to individuals with other neurodegenerative diseases, including FTD, PDD, PD and ALS." (PMID 40665049, 2025). "It is interesting to point out that APOE variants are also considered as a risk factor for other neurodegenerative diseases, such as Alzheimer's disease, and they are also related to inflammation, a common process found in neurodegeneration." (PMID 39996490, 2025). "To identify systemic proteomic changes associated with APOE ε4 carriers who develop neurodegenerative diseases, we used the Global Neurodegeneration Proteomics Consortium (GNPC) dataset." (PMID 40665049, 2025). "Second, our data support reconceptualizing APOE ε4 not only as a disease-specific risk factor but also as a broader susceptibility allele contributing to shared pathogenic mechanisms across neurodegenerative diseases." (PMID 40665049, 2025). "While APOE genotyping can inform treatment decisions, it raises ethical concerns due to the broader implications of disclosing genetic risk information for neurodegenerative diseases." (PMID 40761402, 2025). "Emphasizing the link between ApoE and the risk of pathogenesis in various neurodegenerative diseases is imperative for human disease diagnosis, risk assessment, prevention, and treatment." (PMID 39944166, 2025). "ApoE is a critical gene involved in lipid metabolism and neuronal repair processes, with its variants: ApoE2, ApoE3, and ApoE4 playing distinct roles in neurodegenerative diseases." (PMID 40794785, 2025). "Different APOE isoforms (E2, E3, E4) are associated with different risks of cardiovascular and neurodegenerative diseases." (PMID 41234028, 2025). "Different APOE isoforms (E2, E3, E4) are associated with different risk of cardiovascular and neurodegenerative diseases." (PMID 41234028, 2025). "Despite this, a key strength of our study is the demonstration that a well-established risk variant for one neurodegenerative disease (APOE ε4 in AD) also exerts a conserved molecularsignature across multiple neurodegenerative conditions." (PMID 40665049, 2025). "Apoe (apolipoprotein E) is another well-studied gene that encodes a protein playing a central role in lipid metabolism, neurobiology, and neurodegenerative diseases." (PMID 41134910, 2025). "Future directions highlight the importance of personalized medicine based on individual ApoE genotypes, early biomarker identification for risk assessment, and investigating ApoE4’s role in other neurodegenerative diseases." (PMID 39996715, 2025). "Chromosome 19 has a high gene density and contains key genetic factors related to brain aging and neurodegenerative diseases, including APOE, which is strongly linked to AD34." (PMID 40456753, 2025). "The effect of APOE polymorphism on various neurodegenerative diseases also was investigated through a number epidemiological and neuropathological studies carried out in affected patients." (PMID 41282061, 2025). "Despite the deleterious impact of APOE ε4, little is known about the biological mechanisms underlying this effect and if, or how, it changes across the different neurodegenerative diseases." (PMID 40665049, 2025). "If all APOE ε4 carriers share a common underlying biological vulnerability to neurodegeneration, an important question is what determines which specific neurodegenerative disease they develop." (PMID 40665049, 2025). "ApoE also governs vascular health, an area of significance given the strong association between vascular pathology and neurodegenerative diseases." (PMID 39944166, 2025).
neurodegenerative disease (continued). "Apolipoprotein E (APOE), a secreted protein, traditionally recognized for its role in lipid metabolism and neurodegenerative diseases, is increasingly implicated in immune regulation and cancer progression." (PMID 40963562, 2025). "Numerous studies have demonstrated the multifaceted impact of ApoE alleles on neurodegenerative diseases." (PMID 39944166, 2025). "Over 11,000 plasma and cerebrospinal fluid proteomic samples reveal that the APOE ε4 genetic variant is associated with a systemic pro-inflammatory signature in a variety of neurodegenerative diseases." (PMID 40665049, 2025). "APOE polymorphism influences the risk of occurrence and the rate of progression in several cardiovascular and neurodegenerative diseases." (PMID 41282061, 2025). "We found three clusters defined mainly by genetic variants found in MAPT, APP, and APOE, considering known variants associated with AD and other neurodegenerative disease genetic architectures." (PMID 38693203, 2024). "Genes implicated in both monogenic neurodegenerative disease and risk genes are related to microglia and immune pathways, such as APOE, TREM2, and TBK1, many of which were also identified in our microglial transcriptomic and proteomic data." (PMID 38923692, 2024). "The associations of TMEM106B SNPs with the APOE gene expression and several neurodegenerative diseases also point in that direction." (PMID 38674351, 2024). "Apolipoprotein E (ApoE) polymorphisms modify the risk of neurodegenerative disease with the ApoE4 isoform increasing and ApoE2 isoform decreasing risk relative to the ‘wild-type control’ ApoE3 isoform." (PMID 39185235, 2024). "In the context of neurodegenerative diseases, VD deficiency is significantly associated with disease occurrence, and low serum levels of VD in conjunction with the APOE ε4 allele can synergistically affect disease progression." (PMID 38566155, 2024). "A study has reported that capsaicin attenuates ROS production in BV2 cells treated with apolipoprotein E, which is known as a genetic risk factor for neurodegenerative diseases." (PMID 39409690, 2024). "The polymorphic nature of ApoE is a significant risk factor for neurodegenerative diseases like AD and cardiovascular disease (CVD)." (PMID 39857613, 2024). "Similar phase-separation droplets, lipid droplets (LDs), surrounded by a layer of lipids and proteins, act as inert cellular reservoirs and are associated with ApoE and neurodegenerative diseases." (PMID 36817952, 2023). "This study indicates a common pathogenic mechanism of ApoE in various neurodegenerative diseases, including AD and PD." (PMID 36817952, 2023). "The ApoE gene allelic variant, ε4, is associated with a greater risk for neurodegenerative diseases." (PMID 36710921, 2023). "To compare our findings to a genetic variant with known association with neurodegenerative diseases and aging, we made similar analysis with the frequencies of APOE ε4 allele, which showed a highly significant decrease with age (p = 3 × 10−43)." (PMID 36936421, 2023). "Lobar hemorrhages are often the distinguishing feature of amyloid angiopathy, a degenerative disease thought to be related to alleles of the apolipoprotein E gene, allowing for increased amyloid deposition within vessel walls." (PMID 36631839, 2023). "Instead, NDR1/2 KO brains had significant increases in proteins associated with human neurodegenerative diseases (e.g., ApoE, Htt, APP, and PRNP), highlighting similarities between this mouse model and human disorders." (PMID 36446521, 2023). "ApoE expression regulation and ApoE gene polymorphism play important roles in neurodegenerative diseases such as AD and PD, and other diseases." (PMID 35411309, 2022). "Several other critical proteins linked to neurodegenerative diseases have also been experimentally validated as CaMBPs, including APOE (AD, FTD, PD, LBD), calcineurin (PP2B; AD, FTD, PD, HD, MS), CaMKII (AD, FTD, PD, HD), and many others." (PMID 36421678, 2022).
neurodegenerative disease (continued). "Remarkably, new APOE genetic variants are still being discovered and provide more insights into the impact of the APOE genotype in neurodegenerative diseases." (PMID 36153580, 2022). "Future research on the complex interplay between apoE, various neuropathologies, immunomodulation, and synaptic function will help to shed light on the pathogenic mechanisms of AD and other neurodegenerative diseases." (PMID 36348357, 2022). "As a proof-of-concept, apolipoprotein E4 (ApoE4), implicated in neurodegenerative diseases, was successfully internalized and degraded in the lysosome by the Poly(M6Pn)-bearing anti-ApoE4 antibody." (PMID 35784393, 2022). "Having a parental history of Alzheimer’s increases the risk of developing the neurodegenerative disease, as does carrying at least one ɛ4 allele of apolipoprotein E (ApoE), which increases the risk of AD threefold for each allele." (PMID 35683633, 2022). "Therapeutics enhancing genes associated with ApoE production and its lipidating receptors produce salutary outcomes in various animal models of neurodegenerative diseases, including AD." (PMID 33924200, 2021). "Genetic polymorphisms associated with neurodegenerative diseases (i.e., APOE-ε4 allele, COMT Val/Met alleles) have been linked to both structural and functional neuronal abnormalities in healthy individuals." (PMID 33540525, 2021). "Apolipoprotein E (apoE) is associated with cerebrovascular and neurodegenerative diseases, such as late onset AD and PD." (PMID 33802165, 2021). "APOE gene polymorphism is associated with many diseases, especially neurodegenerative diseases such as Alzheimer’s disease." (PMID 32978453, 2020). "Apolipoprotein-E (APOE) genotype polymorphism is considered to be the most common polymorphism in neurodegenerative diseases and has been consistently linked to normal cognitive decline in AD and MCI patients." (PMID 32848713, 2020). "Reduced levels of and sensitivity to estrogen, exacerbated by both the APOE ε4 allele and menopause, likely makes older women particularly vulnerable to neurodegenerative disease." (PMID 32859588, 2020). "For example, the epsilon 2 and epsilon 4 alleles of apolipoprotein E are associated with extreme longevity and late‐onset neurodegenerative disease, respectively." (PMID 31560163, 2019). "They found that older patients with genotypes associated with neurodegenerative disease, such as apolipoprotein E, exposed to chemotherapy showed a clinically meaningful decrease in self-reported cognitive function at 24 months." (PMID 30746636, 2019). "The epsilon 4 allele of ApoE is also a risk variant for late‐onset neurodegenerative diseases and is thought to contribute to the pathogenesis of Alzheimer's disease via multiple different pathways (Yamazaki, Painter, Bu, & Kanekiyo, 2016)." (PMID 31560163, 2019). "While a number of important questions remain, we hope these initial findings will serve as a basis for the further study of APOE-associated alterations in astrocyte metabolism and future treatments of AD and other neurodegenerative diseases." (PMID 30791549, 2019). "Mutations in various phagocytosis genes (TREM2, complement receptor 1, CD33, APOE, etc.)were also implicated as risk factors for neurodegenerative diseases." (PMID 28340576, 2017). "The human APOE gene has three polymorphic alleles that influence the risk for various types of cancer and neurodegenerative diseases." (PMID 26817942, 2016). "Our APOE genotyping protocol can be used in addressing the impact of APOE polymorphism on disease risk, and notably in clinical assessments that predict the risk for a variety of vascular and neurodegenerative diseases." (PMID 26754117, 2016). "As APOE genotype predicts the risk for a variety of vascular and neurodegenerative diseases, it is critical to develop rapid and cost-effective methods to analyze APOE gene polymorphism." (PMID 26754117, 2016).